YBX1 (Y-box binding protein 1)
Diseases named in the same sentence as YBX1 in open-access papers (continued):
Sharing a sentence is not in itself a finding about the gene and the disease.
tumor (continued). "Increasing the expression of Y-box binding protein 1 (YB-1), which plays a role in transcription and translation, supports cell proliferation and inhibits apoptosis, tumor invasion, metastasis, and angiogenesis." (PMID 35087619, 2022). "Although more than 1,000 GSDME-binding proteins were detected in the PDAC tumour cells, among the transcriptional regulatory proteins, transcription factor Y-box-binding protein 1 (YBX1) drew our attention." (PMID 35292781, 2022). "Current studies have identified the carcinogenic role of NSUN5 and YBX1 in CRC tumor cells, but their expression and function in the immune microenvironment remained unclear." (PMID 36211353, 2022). "Taken together, these findings indicate that YBX1 regulates hY4F sorting into EVs in vivo, and that the accumulation of hY4F in the EVs of donor cells as a result of YBX1-KO inhibits tumor cell progression." (PMID 35410432, 2022). "To test the function of NF-κB signaling pathway in YBX1 induced tumor progression, we investigated the effect of a specific inhibitor of NF-κB pathway, IMD-0354." (PMID 35410432, 2022). "To better understand the role of YBX1 in promoting tumor progression through hY4F in vivo, we studied the effect of subcutaneous injection of A549 cells into nude mice." (PMID 35410432, 2022). "We have found that tumor-secreted VEGF-A induced MDR1 mRNA upregulation in NECs through Y box-binding protein 1 activation." (PMID 34226586, 2021). "HMGA1 and ILF2 were highly expressed in tumor stem cell-like cells, while YBX1 was highly expressed in both monocyte macrophages and tumor stem cell-like cells." (PMID 34527669, 2021). "The tumor stem cell score based on the one-class logistic regression (OCLR) algorithm showed that HCG18 and its regulated transcription factors HMGA1, ILF2, and YBX1 positively correlated with the degree of tumor undifferentiation." (PMID 34527669, 2021). "HCG18 participates in vascular invasion of HCC by regulating macrophages and tumor stem cells through three key transcription factors, YBX1, ILF2, and HMGA1." (PMID 34527669, 2021). "A series of downstream target genes of YBX1 are oncogenes that are involved in malignant growth, chemoresistance, metastasis, tumor angiogenesis, and stem-like properties." (PMID 34976785, 2021). "An integrative analysis of both proteomics and transcriptomics data showed that YBX1 is expressed in tumor tissue, and it acts as a regulator of tumor invasion." (PMID 34631760, 2021). "Taken together, these data indicate that YBX1 promotes tumor aggressiveness through either direct regulation of EMT genes or indirect modulation of glycolysis." (PMID 34440660, 2021). "In gastrointestinal cancer cells, TP53TG1 plays a tumor suppressive role through the sequestration of the RNA binding protein YBX1, thus blocking its oncogenic activity." (PMID 34564314, 2021). "One of the representatives for RBPs is YBX1, which has been recognized as a marker for tumor aggressiveness and poor prognosis in various cancers such as breast, ovary, and liver cancer 92-94." (PMID 34335937, 2021). "Western blot analysis of tumor tissues showed that MUC1 overexpression partially rescued the effect of YBX1 silencing on CD133, Oct-4, MMP9, E-cadherin, β-catenin, and Snail expression." (PMID 34976785, 2021). "As classic tumor biomarkers, YBX1 and MUC1 are significant in the occurrence and development of various tumors." (PMID 34976785, 2021). "As a well-known DNA/RNA binding protein, YBX1 has been reported involved in some lncRNAs perform their biological functions during the tumor development and progression." (PMID 34131399, 2021). "Y-box-binding protein 1 (YB-1) is a well-known oncoprotein regulating tumor cell growth, invasion, metastasis, drug resistance, and angiogenesis." (PMID 34306080, 2021). "In that research, they claimed the tumor-promoting role of circ_0008035 in GC cell proliferation and invasion in vitro via miR-375/Y-box binding protein-1 axis." (PMID 32165864, 2020).
tumor (continued). "The Y-box binding protein 1 is a multifunctional protein whose expression is significantly increased in a great number of tumour entities." (PMID 32824741, 2020). "To further examine the effects of YBX1 on tumor growth, drug sensitivity and autophagy via p110β signaling in vivo, we used nude mice bearing NSCLC xenografts." (PMID 32561752, 2020). "It was recently reported that IMPDH1 cooperated with metastasis-related protein Y-box binding protein 1 (YB-1) and thus promoted tumor metastasis." (PMID 33520699, 2020). "YBX1 regulates gene transcription and translation; on the other hand, YBX-1 is controlled by oncogenes or tumor-suppressor genes." (PMID 33312753, 2020). "Alternative strategies depend on aberrant expression of oncoproteins such as Y-box-binding protein 1 (YB-1) or exploit hypoxic conditions in the tumor core by using a hypoxia-inducible factor 1α (HIF1α)-dependent promoter." (PMID 33202717, 2020). "More recently, tRNA fragments that act as tumor suppressors were reported to downregulate RNA-binding protein YBX1, which consequently led to destabilization of many pro-oncogenic transcripts." (PMID 31616639, 2019). "Our analysis suggests YBX1 as a potential regulator of these key molecules involved in tumor invasion and thus as a promising target for development of new therapeutic strategies for GBM." (PMID 31358880, 2019). "Among these, ITGB8, RELN, and SPP1 were the top tumor-promoting candidates significantly downregulated (FDR < 0.05) by YBX1 knockdown in the ECM-receptor interaction pathway." (PMID 31481087, 2019). "Put together, all these studies are in support of the key role of YBX1 in regulating key players in the processes such as tumor growth and invasion and thus in GBM biology in general." (PMID 31358880, 2019). "We observed positive expression of YBX1 in tumor tissues in the IHC analysis and interestingly, all of the interacting proteins selected showed concordance with YBX1 expression and showed positive expression in the tumor tissues as compared to the control." (PMID 31358880, 2019). "Collectively, the results from the in vivo tumor xenograft models indicated that silencing of G3BP1 suppresses RCC tumor cell metastasis through YBX1/G3BP1-SPP1 signaling pathway." (PMID 31481087, 2019). "Regarding tumour size, YBX1 expression was significantly higher in T2 (2–3 cm) tumours than in T1 (<2 cm) tumours (p = 0.012)." (PMID 31461477, 2019). "We also found that the transcriptional activation of HDAC5 is partly mediated by HOXC-AS3 in the tumor progression of GC through binding to YBX1, thus facilitating GC cell proliferation and migration." (PMID 30286788, 2018). "Additional examples of RBPs with known oncogenic or tumor suppressive functions that have been linked to EV miRNA sorting include Annexin A2 (ANXA2), Kirsten rat sarcoma (KRAS), Y-box binding protein 1 (YB-1), MEX3C, and Argonaute 2 (AGO2)." (PMID 30071693, 2018). "We further certified that the prolific and anti-apoptotic effects of YBX1 were largely dependent on glycylosis as 2-DG or lower glucose sufficiently blocked the tumor-promoting effects of YBX1." (PMID 29029484, 2017). "Our results suggest that YBX1 is controlled via complex regulatory mechanisms involving tumor stroma interaction and signal transduction processes." (PMID 26779809, 2016). "More importantly, a series downstream of YBX1 targeting genes are oncogenes which involved in malignant growth, chemotherapy resistance and tumor angiogenesis." (PMID 27384875, 2016). "This defines YBX1 as an oncogenic enhancer that can regulate tumour angiogenesis via release of secreted modulators into the extracellular microenvironment." (PMID 25980435, 2015).
tumor (continued). "Despite these reports, YBX1 has also been reported to play tumour-suppressive roles in cell proliferation and development, indicating diverse cellular mechanisms of action." (PMID 25980435, 2015). "Taken together, we provide the first evidence that YBX1 functions as a tumor promoter via NF-κB activation, and phosphorylation of S165 of YBX1 is critical for this function." (PMID 26318844, 2015). "While this paper was under review, a possible role of tRFs as tumor suppressors binding to oncogenic RNA-binding protein YBX1, displacing pro-oncogenic transcripts has been described." (PMID 26374501, 2015). "RSK phosphorylates Y-box binding protein-1 (YB-1), an oncogenic transcription/translation factor, highly expressed in TNBC (~70% of cases) and associated with poor prognosis, drug resistance and tumor initiation." (PMID 23593654, 2013). "These properties are in direct contrast to those of YB-1, where high levels of YBX1 mRNA or protein in tumours have been associated with poor patient prognosis." (PMID 24260353, 2013). "We detected p65 and p-p65 in nude mice tumor tissue sections by immunohistochemical staining, and the results showed that the protein expression of p65 and p-p65 was also significantly reduced after YBX1 was down-expressed." (PMID 41507134, 2026). "In vivo studies demonstrated that inhibiting YBX1 with the small-molecule SU056 reduces tumor size." (PMID 41994112, 2026). "Tumours with high YBX1 mRNA expression consistently exhibited conserved transcriptional programmes enriched for cell cycle, mitotic, RNA processing, and signalling pathways, patterns that were also reflected at the protein level by concordant pathway associations with elevated YB-1 abundance." (PMID 42196325, 2026). "Additionally, over 136,000 EV-associated circRNAs have been identified as potential biomarkers, with YBX1 mediating their packaging into EVs, indicating that EVs are rich in circular RNAs involved in tumor progression." (PMID 41230432, 2026). "This indicates that YBX1 regulates tumor growth through the CDC25a pathway." (PMID 40799245, 2025). "In addition to its roles in tumor progression and other biological processes, YBX1 is also emerging as a key player in immune regulation." (PMID 40799245, 2025). "Nuclear YBX1 promotes aggressive tumour behaviour and cellular invasiveness." (PMID 40855961, 2025). "However, additional research is required to explore the biological functions of YBX1 beyond its role in regulating mRNA stability and promoting tumour progression." (PMID 40088428, 2025). "Additionally, in OSCC, YBX1 mRNA levels were significantly upregulated in tumor tissues relative to their matched adjacent normal tissues." (PMID 41436732, 2025). "Interestingly, Zbp1−/− tumor cells showed lower expression of H2afz, Nme1, Ran, and Ybx1, but higher expression of Nupr1 compared to WT cells." (PMID 41430036, 2025). "In addition to its role as a transcription factor in tumors, YBX1 interacts with downstream factors to further promote tumor progression." (PMID 40799245, 2025). "The upregulated expression of YBX1 in multiple tumours correlates with poor prognosis." (PMID 40088428, 2025). "In summary, YBX1 promotes tumor progression through its transcription factor activity, exerting its effects via various downstream targets such as MUC1, CDC25a, NANOG, Kindlin-2, G3BP1, AURKA, SPP1, the EGFR-RAS-MAPK axis, CORO1C, among others, depending on the specific tumor type." (PMID 40799245, 2025). "Furthermore, the knockout of YBX1 reverses resistance to immunotherapy by blocking PD-L1 expression and activating T cells in the tumor microenvironment, providing a new strategy for immunotherapy." (PMID 40675967, 2025). "Building on this perspective, the present review systematically summarizes the multifaceted roles of YBX1 in tumor biology and immune regulation, highlighting its potential as a therapeutic target and the challenges in translating these insights into clinical applications." (PMID 41346602, 2025).
tumor (continued). "For example, TUG1 sponges miR-141 and miR-340, resulting in increased PD-L1 and CD47 on tumors, as well as TUG1 binding the transcription factor YBX1, further enhancing the transcription of these immune-evasive signals, thus establishing a self-perpetuating feedback loop that promotes tumor escape." (PMID 41154428, 2025). "TUG1, upregulated by METTL3-mediated m6A, regulates PD-L1 and CD47 by sponging miR-141/miR-340 and interacting with YBX1; its knockdown inhibits tumor growth, enhances CD8+T/M1 macrophage infiltration, activates CD8+T via PD-L1, and boosts macrophage phagocytosis through CD47." (PMID 40352941, 2025). "YBX1 is a highly conserved multi-functional protein and participates in a wide range of biological processes, including embryonic development, tissue repair, and tumor progression." (PMID 40083711, 2025). "However, the regulatory effects of YBX1 and its interacting molecules, as well as the detailed mechanisms of these interactions on tumor progression, require further investigation." (PMID 40799245, 2025). "YBX1 expression in tumour tissues was markedly increased compared to normal tissues." (PMID 40088428, 2025). "Beyond intrinsic tumor cell functions, YBX1 also modulates the tumor immune microenvironment." (PMID 41346602, 2025). "Additionally, YBX1 inhibition can reverse chemotherapy or targeted therapy resistance, increasing drug sensitivity and achieving multi-layered anti-tumor effects." (PMID 41346602, 2025). "A forest plot highlighted key oncogenic factors such as SNX5, YBX1, TPM3, and RAB7A, which were significantly associated with poorer survival and may drive tumor progression." (PMID 41031219, 2025). "Furthermore, NSUN2 promotes SLC7A11 mRNA stability via the recognition role of YBX1, which resists the ferroptosis pathway of tumour cells to promote survival." (PMID 40860147, 2025). "In addition, analysis of clinical samples revealed that YBX1 and RNF115 were upregulated in HCC tumours and associated with poor prognosis." (PMID 40088428, 2025). "In addition, DCA inhibited tumor growth rate more significantly in mice bearing Ybx1 knockdown cells compared with control." (PMID 40812419, 2025). "Thus, YBX1 plays a pivotal role in tumor immunity, molecular regulation, auto-immune diseases, and immunotherapy." (PMID 39727969, 2024). "Knocking down YBX1 in DLBCL led to a decrease in tumor cell viability." (PMID 39588389, 2024). "Furthermore, research has demonstrated that chemoresistant tumor cells can promote the binding of YBX1 to the PD-L1 promoter region, thereby promoting the transcription of PD-L1 and facilitating immune evasion in liver cancer." (PMID 38520004, 2024). "Furthermore, we identified YBX1 as a novel CDKL1-interacting protein and elucidated a new mechanism by which CDKL1 affects tumor immune evasion through the YBX1/PD-L1 axis." (PMID 38520004, 2024). "Thus, YBX1 emerges as a promising target for immunotherapy due to its dual role in the immune system, tumor immune responses, and immunotherapeutic outcomes regulation." (PMID 39727969, 2024). "In addition, a recent study reported that YBX1 negatively regulates cell PANoptosis, but positively regulates chemoresistance and tumor progression in GC." (PMID 38965605, 2024). "For instance, if a tumor shows upregulation of YBX1-mediated drug efflux pumps, co-administering an YBX1 inhibitor might overcome resistance." (PMID 38255791, 2024). "Additionally, tumour tissues from the KMT2D‐ or YBX1‐knockdown groups showed reduced expression of Ki‐67, a well‐established marker of cell proliferation." (PMID 38967349, 2024). "In mouse xenograft model, knockdown of either KMT2D or YBX1 inhibited tumour growth." (PMID 38967349, 2024). "CircNEIL3 inhibits tumour metastasis by recruiting the E3 ubiquitin ligase Nedd4L to degrade YBX1." (PMID 38378679, 2024).
tumor (continued). "YBX1 can regulate the immune response and immune cell activation by affecting the expression of various immune factors, including interleukins, chemokines, and tumor necrosis factors, participating in anti-tumor immunity." (PMID 39727969, 2024). "Furthermore, the role of YBX1 in neurogenesis is also discussed, emphasizing its impact on the tumor microenvironment." (PMID 38255791, 2024). "Additionally, YBX1 promotes the polarization of M1 macrophages towards a tumor-supportive M2 phenotype." (PMID 39727969, 2024). "In the present study, we searched for possible candidate downstream mRNAs of circRAD23B by RNA-seq and found that YBX1 presented the largest differential fold change after knockdown of circRAD23B, which is a reported tumour promoter and chemoresistance inducer in OC." (PMID 38273320, 2024). "YBX1 also facilitates tumor immune evasion by modulating immune cells." (PMID 39727969, 2024). "For instance, high nuclear YBX1 might indicate poor prognosis, while cytoplasmic localization could suggest a less aggressive tumor." (PMID 38255791, 2024). "YBX1 emerges as a pivotal regulator in orchestrating this phenomenon, exerting its influence on the infiltration of immune cells and the expression of immune molecules within the tumor microenvironment." (PMID 39727969, 2024). "Furthermore, the expression levels of ALYREF and YBX1 were significantly correlated with immune infiltration of the tumor microenvironment and immune-related modulators." (PMID 38238581, 2024). "Understanding how YBX1 influences phenotypic plasticity could illuminate the mechanisms underpinning tumor progression and open up new avenues for targeted therapies." (PMID 38255791, 2024). "Additionally, in NSCLC, long non-coding MELTF Antisense RNA 1 has been shown to directly bind and displace the RNA-binding protein YBX1, which is involved in tumor development, thereby activating ANXA8 transcription and promoting tumorigenesis." (PMID 39716068, 2024). "In addition, KMT2D and YBX1 were significantly overexpressed in the tumour tissues of patients with advanced TNM stage and recurrence." (PMID 38967349, 2024). "Furthermore, the correlation became more significant when focusing on the cells with TAGLN2- and YBX1-positive signals (TAGLN2+YBX1+) in all tumor and paired control tissues (r = 0.6820, P < 0.0001) and only tumor tissues (r = 0.6882, P < 0.0001)." (PMID 39168971, 2024). "Research indicates that heightened YBX1 expression can promote immune escape in tumor cells." (PMID 39727969, 2024). "Its involvement in regulating tumor immunity is well-established, and targeting the YBX1 signaling axis holds the potential for reversing tumor immune escape and multidrug resistance, activating the immune response, and restoring the antitumor effects of chemotherapy." (PMID 39727969, 2024). "TET2’s oxidation weakens YBX1’s binding affinity to mRNA because YBX1’s recognition ability for 5hmC-modified mRNA is weaker than that for 5mC, thus indirectly inhibiting YBX1’s function by weakening its binding to target mRNA, thereby reducing mRNA stability and inhibiting tumor development." (PMID 39497723, 2024). "However, the exact contribution of YBX1 to this process and its implications for tumor heterogeneity and therapeutic responses necessitate further exploration." (PMID 38255791, 2024). "Moreover, there was a close positive correlation between the expression of TAGLN2 and YBX1 in DAPI+ cells of both tumor and paracancerous tissues (r = 0.1657, P = 0.027)." (PMID 39168971, 2024). "Among patients without metastasis at tumour diagnosis and under AbA, a marginal association between YBX1 rs10493112 and progression-free survival was detected (log-rank test, p = 0.056)." (PMID 39337362, 2024). "YBX1 is also involved in tumor progression via the PI3K/Akt/mTOR signaling cascade." (PMID 36740668, 2023).